BDNF (brain derived neurotrophic factor)
Diseases named in the same sentence as BDNF in open-access papers (continued):
Sharing a sentence is not in itself a finding about the gene and the disease.
depression (continued). "Although P-selectin, thromboglobulin, and MTHFR, a key modulator of purine and thymidylate biosynthesis, play a critical role in thrombosis, and their alterations have been observed in subjects with depression, definitive potential relationship with BDNF is actually missing." (PMID 35911513, 2022). "A preponderance of clinical and experimental data indicates an essential role for BDNF in the pathophysiology of depression, leading to the “Neurotrophin Hypothesis of Depression”." (PMID 36466807, 2022). "Recent studies have also concluded that BDNF is correlated with depression." (PMID 35510613, 2022). "This prodepressant role of mesocorticolimbic BDNF signaling is in direct contrast to the antidepressant-like actions of BDNF in the HC, which emphasizes the circuit-specific nature of molecular mechanisms involved in stress-induced depression." (PMID 36499323, 2022). "Additionally, diet can promote the production and secretion of brain-derived neurotrophic factor (BDNF), a peptide implicated in synaptic plasticity and neuronal survival, whose levels are decreased in pregnant women with depression." (PMID 35297499, 2022). "Since BDNF, associated with the onset and pathophysiology of depression and mood disorders, is reduced by stress, stress-induced BDNF reduction may contribute to the onset of depression and other mood disorders." (PMID 35897310, 2022). "In addition, propolis attenuates the injury of nerve cells in the hippocampal region and restores the serum levels of brain-derived neurotrophic factor (BDNF) and dopamine (DA) in mice with alcohol-induced depression." (PMID 35334870, 2022). "A study revealed that MAR can improve diabetes-induced depression by increasing BDNF levels." (PMID 36014776, 2022). "The expression of BDNF is related to the pathogenesis of depression." (PMID 35663561, 2022). "Thus, WT and BDNF het-Met mice displayed specificity to either test for anxiety-like behavior and depression-like behavior, respectively." (PMID 34848858, 2022). "The observation of a possible link among BDNF, depression, and miRNAs related to atherothrombosis and depression in obesity is novel and may lead to a wider use of BDNF as a CV risk biomarker in this specific subject group." (PMID 35911513, 2022). "The changes in the levels of BDNF are considered biomarkers for depression and play a vital role in the development of depression, and its restoration may underlie the therapeutic efficacy of antidepressant treatment." (PMID 36686688, 2022). "Our results provide new insights into some of the bases for EGCG action in depression, which we hypothesize may involve modulation of IL-1β peripheral blood levels, BDNF expression in the hippocampus and neuronal ultrastructural damage in CUMS disorder." (PMID 35939172, 2022). "A recent study demonstrated that BDNF DNA methylation was related to depression and could be used as a blood biomarker for MDD." (PMID 35283726, 2022). "Further, deficits in BDNF signaling may contribute to the evolvement of major diseases like Alzheimer’s disease and major depressive disorder." (PMID 36555576, 2022). "In addition, we explored the role of MT receptors and BDNF in the hippocampus to ascertain the mechanism of action of the melatonin analogue in a PNS rat model of depression." (PMID 36142262, 2022). "The level of BDNF in the neurons of patients with depression is very low." (PMID 36844911, 2022). "Indeed, BDNF has both pro- and anti-depressant effects, dependent on brain region, confirming a strong, though region-specific, contribution of BDNF to depression pathogenesis." (PMID 36142325, 2022). "Lowered BDNF levels were observed with both mania and depression in BD." (PMID 35163764, 2022).
depression (continued). "We therefore speculated that locally increased BDNF in the ACC may be secreted to other brain regions (such as the hippocampus) as a compensatory mechanism after depression-like behaviors appear." (PMID 35401106, 2022). "Different neurotrophic factors are highly connected to depression, notably BDNF." (PMID 35955633, 2022). "Major depressive disorder is a key modulator of adult neurogenesis and BDNF levels." (PMID 36555576, 2022). "The results revealed that the main effect of BDNF val66met on adolescent depression was not significant, which means that the allele present at the polymorphic locus did not predict depression." (PMID 36297314, 2022). "This implies that a decreased BDNF level can be an early predictor of depression in PwS." (PMID 35287688, 2022). "Similarly, treatment with vortioxetine (an inhibitor of the serotonin transporter; 5–15 mg over 4 weeks) increased the plasma BDNF levels in patients with major depression disorder, based on their basal values." (PMID 35684488, 2022). "Therefore, this narrative review will focus on these pathways in processes such as neuroinflammation, stress, microbiota, and brain-derived neurotrophic factor dysregulation in depression." (PMID 35955633, 2022). "Besides, BDNF plays an important role in adult neurogenesis, and there is evidence that depression is related in part to insufficient neurogenesis and neurotrophic activity." (PMID 35837277, 2022). "Perhaps the elevated BDNF levels represent more of high stress levels associated with the acute phase of psychosis and depression, rather than indicating a specific pathophysiological pathway associated with schizophrenia." (PMID 35447946, 2022). "Antidepressants may increase or normalize the otherwise low levels of cerebral BDNF in patients with major depressive disorder." (PMID 35668445, 2022). "The effects of BDNF on depression is specific to its target site." (PMID 36499240, 2022). "We take CREB/BDNF as a target to explore whether inhibiting the development of pain will avoid the occurrence of depression-like behaviors as well as anxiety." (PMID 35401106, 2022). "CFSS resulted in the upregulation of proBDNF and downregulation of BDNF in the hippocampus, both of which could potentially synergistically elicit depression- and anxiety-like behaviors." (PMID 35462923, 2022). "In another study, the relative abundance of the Lachnospiraceae family increased in the gut microbiota of depression patients who had treatment, and the relative abundance of some genera in Lachnospiraceae was positively correlated with brain-derived neurotrophic factor levels." (PMID 35458204, 2022). "Furthermore, a study found that supplements with probiotics ameliorated the depression-like behaviors of rats with epilepsy through upregulating the expression levels of BDNF and nerve growth factor." (PMID 36358502, 2022). "Interestingly, treatment with Mg and vitamin D augments serum BDNF levels in patients affected by depression and obesity." (PMID 35563524, 2022). "Therefore, alarin can potentially alleviate depression by up-expressing BDNF, as evidenced by the increased expression of BDNF mRNA in the prefrontal cortex and hippocampus of UCMS-treated mice after alarin administration." (PMID 36506414, 2022). "The CREB/BDNF pathway plays an important role in both pain and depression." (PMID 35401106, 2022). "These compounds not only induce rapid antidepressant-like effects in animal models of depression but also share many mechanisms of antidepressant activity with ketamine, including involvement of the BDNF and mTOR pathways and dependence on AMPA receptor activation and serotonergic system activity." (PMID 35215237, 2022). "In the present study by using data from an Italian cohort of obese individuals, we identified a significant negative association between depression scores and BDNF plasma levels, a finding that was modified by elevated inflammatory levels of IFN-γ." (PMID 35911513, 2022).
depression (continued). "Reduced BDNF levels have been observed in depression patients and may contribute to reduced hippocampal volume and cognitive deficits seen in depression." (PMID 35256586, 2022). "Oxidative stress may be involved in the increase in vulnerability, as shown in a rat model of social defeat stress (SDS)—a major acute stress that induces a reduction in BDNF levels, but only in animals vulnerable to depression." (PMID 35326190, 2022). "We studied the influence of CLB on anxiety‐ and depression‐like behaviors, social rank, gut microbiota, inflammatory cytokines, and brain‐derived neurotrophic factor (BDNF) after SDTT to explore possible mechanisms related to anti‐inflammatory effects and rebalance of the gut microbiota." (PMID 34878231, 2022). "Hence, the gut microbiota has a promising ability to control BDNF and regulate the development of depression-like behavior." (PMID 36499295, 2022). "Downregulation of miR-124 may provide a strategy for the treatment of depression by activating the BDNF-TrkB, ERK, and CREB signaling pathways in the hippocampus." (PMID 35916975, 2022). "In addition, a recent study by Furuse and colleagues (2019) further implicates the changes in BDNF levels in the nucleus accumbens in the pathophysiology and treatment of treatment-resistant depression." (PMID 36430921, 2022). "Therefore, miR-221 participated in the development of depression through the regulation of the Wnt2/CREB/BDNF signalling pathway." (PMID 35562946, 2022). "Furthermore, OT ameliorates anxiety‐ and depression‐like behaviors by increasing BDNF expression levels and neurogenesis in the hippocampus in a male rodent model of depression." (PMID 35730145, 2022). "From the perspective of depression treatment, the therapeutic effects of antidepressant drugs have been attributed to the increase in the proliferation of neuronal progenitor cells through mechanisms involving up-regulation of hippocampal BDNF levels." (PMID 35501732, 2022). "Additionally, G and M or G and DZ administration also reversed the decreased 5-HTT and BDNF levels in depression." (PMID 35161241, 2022). "Hence, stress and depression disturb BDNF–TrkB receptor signaling, along with the depletion of the downstream ERK and Akt pathways in the hippocampus and prefrontal cortex." (PMID 36499295, 2022). "To date, research suggests that the reuptake inhibition of monoamines, MAO inhibition, NMDA antagonism, and improved brain-derived neurotrophic factor signaling may be mechanistic factors responsible for the treatment of depression from saffron." (PMID 35408474, 2022). "First, melatonin regulates depression, cognition and memory via BDNF-related molecular processes." (PMID 36699021, 2022). "Studies of depression have shown that EA can target BDNF through miR-206 and miR-155." (PMID 35719137, 2022). "Moreover, mounting research shows that BDNF levels are reduced in the postmortem peripheral blood of patients with depression, and some reports have indicated that antidepressant treatment can normalize this." (PMID 35875370, 2022). "BDNF and VEGF levels are generally decreased regionally in the brains of MDD subjects and in preclinical animal models of depression, changes that are associated with neuronal atrophy and reduced neurogenesis, and are reversed by conventional monoaminergic and novel ketamine-like antidepressants." (PMID 35909451, 2022). "Since BDNF is reduced in the onset of depression, the neurotrophic hypothesis has become one of the critical etiologies of antidepressant progression." (PMID 36014336, 2022). "When BDNF and TrkB expressions were decreased, BDNF binds to the low affinity receptor P75 to activate P75 pathway, which can trigger neuron apoptosis and induce depression." (PMID 36417428, 2022).
depression (continued). "The increased pro-inflammatory cytokines can also induce a cascade involving oxido-nitrosative stress, during which the increased nitrite together with the reactive oxygen species mediates the progression of depression likely through down-regulation of BDNF expression." (PMID 35242039, 2022). "Exercise may also alleviate the symptoms of depression by increasing the level of brain-derived neurotrophic factor (BDNF)." (PMID 36233770, 2022). "Recent study revealed that C/EBPβ could downregulated BDNF, indicating C/EBPβ may be a missing link between BDNF and depression." (PMID 36578534, 2022). "Supporting this, different in vitro studies have reported the ability of LpCJLP55-MVs to upregulate the expression of BDNF transcripts, as well as the proBDNF protein, in HT22 hippocampal cells after the induction of depression-associated changes by corticosterone administration." (PMID 36558455, 2022). "These mice showed depression-like behavior, impaired response inhibition, and inflexible learning, supporting the idea that reduced BDNF may lead to depression and schizophrenia through monoaminergic transmission alterations." (PMID 35955546, 2022). "In addition, numerous pieces of evidence suggested that BDNF is one of the key factors in the pathogenesis of depressive disorders, as the BDNF concentrations decreased with increasing depression severity." (PMID 36422003, 2022). "Therefore, our findings aim to demonstrate that the inflammation-activated neuronal C/EBPβ promotes HFD-induced depression by diminishing BDNF expression." (PMID 36578534, 2022). "In stress-associated diseases, including depression, BDNF expression is decreased mainly in the hippocampus." (PMID 35600081, 2022). "Here, we explored how miR-139-5p involves in regulating depression and hypothesized that miR-139-5p could activate the BDNF-TrkB pathway to exert antidepressant-like effects, with a hope to find new depression drug targets." (PMID 35543383, 2022). "In human research, the description of BDNF levels in peripheral blood may be traced back to the early work of Karege, who suggested that major depression was characterized by low serum BDNF levels." (PMID 35757201, 2022). "MiR-139-5p inhibition is likely to have antidepressant-like effects via activating the BDNF-TrkB signaling pathway, and miR-139-5p might be a new depression drug development target." (PMID 35543383, 2022). "Both BDNF dysfunction and neuroinflammation have been found in depression." (PMID 35370823, 2022). "In addition, peripheral BDNF levels correlated with depression severity: the lower the BDNF level, the greater the severity." (PMID 35203890, 2022). "Moreover, we revealed that the novel inflammatory transcriptional factor C/EBPβ played a critical role in HFD-induced depression-like behaviors via downregulating BDNF and promoting AMPARs internalization." (PMID 36578534, 2022). "Therefore, it follows that telomeres and BDNF play a role as intermediaries between loneliness and depression and their relationship with a worse state of health." (PMID 36497531, 2022). "This study aims to elucidate whether baicalein could exert antidepressant effects by attenuating inflammation and increasing BDNF expression, thereby mitigating depression in mice." (PMID 35624812, 2022). "Additionally, the level of BDNF was higher in rats in the CUMS+FMT group, suggesting BDNF contributed to the pathogenesis of depression and alteration of intestinal motility." (PMID 35967846, 2022). "Furthermore, understanding upstream regulators of BDNF expression, such as epigenetic or post-translational modifications like N-glycosylation on pro-BDNF, will help to suggest future biomarkers and therapeutic targets of adolescent depression." (PMID 35875661, 2022). "Besides, Gammaaminobutyric acid (GABA), brain-derived neurotrophic factor (BDNF), and dopamine (DA) also participate in the pathogenetic process of depression." (PMID 36034955, 2022).
depression (continued). "Concerning peripheral BDNF levels in major depression, one review has highlighted platelet function as a possible confounding factor influencing BDNF measurement, with platelets being the major source of peripheral BDNF." (PMID 35836661, 2022). "The targeting of the Shati/Nat8l-BDNF pathway could be a potential therapeutic target for the treatment of depression." (PMID 35916975, 2022). "The involvement of BDNF has been demonstrated in the progression of several brain diseases, including Parkinson’s and Alzheimer’s diseases; patients with such diseases typically present with the comorbidity of depressive disorder." (PMID 35624812, 2022). "This places 5-HT and BDNF as the main targets of new molecules for depression disorders." (PMID 36142808, 2022). "A lower concentration of brain-derived neurotrophic factor (BDNF) in the brain and serum may be associated with depressive disorders." (PMID 36387009, 2022). "Numerous studies reported the crucial role of BDNF in some specific neurobiological processes which may lead to depressive disorders, anxiety-like behavior, and other stress-related mental disorders." (PMID 35508633, 2022). "Moreover, BDNF modulates the activity of various neurotransmitters involved in the pathophysiology of depressive disorders such as glutamate, GABA, serotonin and dopamine." (PMID 35203890, 2022). "In patients with depressive disorders, agomelatine not only showed anti-inflammatory effects but also increased the expression of BDNF, and hence, it may affect brain plasticity in the pathophysiology of MDD." (PMID 36012250, 2022). "BDNF is highly expressed in the hippocampus and is sensitive to the stress response, which can be used as a biological marker of the pathogenesis and course of depression." (PMID 34900345, 2021). "Elevated maternal BDNF was specifically associated with maternally reported anxiety symptoms and not symptoms of depression." (PMID 33462179, 2021). "The purpose of this study is to examine the potential antidepressant-like effects of GSB-106 as demonstrated by an UCMS model of depression in Balb/c mice and to evaluate whether this effect is mediated through amelioration of BDNF/TrkB signaling." (PMID 34948177, 2021). "Neurotrophins, especially BDNF, are known to participate in the pathogenesis of depression." (PMID 33673283, 2021). "A key role of the proinflammatory cytokines IL-6 and TNF-α has in fact been described in depression, moreover, both in patients and experimental models a clear relationship between low levels of BDNF and the presence of anxiety and depression has been suggested." (PMID 34638592, 2021). "As a result, targeting the BDNF–TrkB pathway with small molecular compounds may lead to a new class of therapeutics for the treatment of depression." (PMID 34451801, 2021). "However, in the OBX model of depression, the literature suggests distinct hippocampal BDNF modulations." (PMID 34421682, 2021). "To further confirm a direct role of Pdcd4-mediated BDNF-TrkB signaling pathway in CRS-induced emotional disorders, we next investigated whether blockage of BDNF could boost depression in CRS-treated Pdcd4 ncKO mice." (PMID 32203159, 2021). "Also, we found that depressive patients exhibited hypomethylation in a CpG site of BDNF promoter IV, which adds to the current discussion about the role of methylation in depression." (PMID 34970165, 2021). "The major findings demonstrated the following: (i) increased blood BDNF levels; (ii) improved lower limb muscle strength and aerobic capacity; (iii) improved clinical symptoms, i.e., sleep quality, depression symptoms, pain; and (iv) improved quality of life after a 6-week intervention of WBVT." (PMID 34900203, 2021). "A study in cancer patients with depression showed a significant negative correlation between circulating IL-6 and BDNF, while a positive association was observed in patients with major depressive disorder." (PMID 33985854, 2021).